LEP (leptin)
Diseases named in the same sentence as LEP in open-access papers (continued):
Sharing a sentence is not in itself a finding about the gene and the disease.
breast cancer (continued). "Leptin treatment significantly promoted the growth of MCF-7 breast cancer cells in a dose-dependent manner, whereas no significant growth effect was observed in MDA-MB-231 cells, which are ER negative breast cancer cells." (PMID 29312618, 2017). "A large set of breast cancer cases, and 27 non-cancerous tissue samples of breast were employed for leptin expression recognition using immunohistochemistry staining." (PMID 29121911, 2017). "In the modulation of breast cancer, although leptin is well known to promote growth of breast cancer cells, it does not significantly affect growth of estrogen receptor (ER)-negative breast cancer cells." (PMID 29312618, 2017). "Pretreatment with tamoxifen significantly alleviated leptin-induced increase in the populations of the cells in the S and G2-M phases in MCF-7 cells, whereas no significant change in each phase of the cell cycle was observed in MDA-MB-231 breast cancer cells." (PMID 29312618, 2017). "In the HCC1937 breast cancer cells of group 1, the effect of leptin over cell proliferation was negative at all concentrations evaluated (57.14%)." (PMID 29311755, 2017). "Taken together, our study indicates that BMP9 can inhibit the growth and metastasis of breast cancer cells, which may be related to interaction between pre-adipocytes/adipocytes and MDA-MB-231 cells via leptin signaling pathway." (PMID 28415788, 2017). "In mouse mammary cancer cells, it has been shown that leptin increased the expression of VEGF and its receptor VEGF-R2 suggesting that VEGF may be regulated by leptin." (PMID 27059487, 2016). "Indeed, we have shown that leptin immunodepletion from CAF-derived conditioned media (CAF-CM) substantially reduced the growth- and migration-promoting activities of CAFs on breast cancer cells." (PMID 26899873, 2016). "Leptin significantly influenced proliferation/migration along with VEGF/VEGFR-2 that was highly dependent on a novel unveiled crosstalk between Notch, IL-1 and leptin (NILCO) in breast cancer cells." (PMID 27472371, 2016). "In addition, leptin activation of STAT3 upregulates IL-1 and Notch in breast cancer and markers of cancer stem cells in pancreatic and breast cancer." (PMID 27472371, 2016). "The ability of the FXR ligand to block leptin actions was also reproduced in another ERα-negative breast cancer cell line, SKBR3." (PMID 26899873, 2016). "IL-1 upregulation involves leptin activation of JAK2/STAT, PKC, p38, MAPK/ERK1/2, PI-3K/AKT1 and JNK suggesting that multiple leptin-induced signaling pathways can affect leptin-IL-1 crosstalk in breast cancer." (PMID 27472371, 2016). "The aim of the current study was to evaluate the role of leptin, as a mediator of the tumor-stroma interaction, in regulating breast CSC activity using breast cancer cell lines and patient-derived breast cancer cells isolated from metastatic ascites and pleural effusions." (PMID 26556856, 2016). "Our findings also indicated the crucial role of PKM2 in leptin-mediated EMT, and PKM2 might be one of the key points and potential targets for breast cancer therapy." (PMID 27769315, 2016). "Now, by using siRNA strategy, we have demonstrated not only that Sam68 is mediating both insulin and leptin stimulated cellular metabolism, but also its participation in the leptin and insulin dependent activation of MAPK and PI3K signalling pathways in breast cancer cells." (PMID 27415018, 2016). "HNK treatment efficiently inhibits leptin-induced EMT as well as migration of breast cancer cells, therefore, we hypothesize that HNK may also inhibit leptin-induced mammosphere formation." (PMID 26359358, 2015). "Centering our interest in the role of leptin in this E0771 mammary in vitro/in vivo tumor model, we found that, contrary to most breast/mammary tumor cell lines, E0771 cells do not express leptin." (PMID 25599228, 2015).
breast cancer (continued). "In our study, the human adipokine chip test of the co-culture supernatant of MCF-7 cells and adipocytes revealed some altered proteins which are reported to be involved in the regulation of proliferation and metastasis of breast cancer cells, such as IGFBP-2, IL-6sR, IL-8, leptin, MIF, and TGF-β." (PMID 25747684, 2015). "HNK inhibits leptin-induced Wnt1, MTA1 and β-catenin expression in breast cancer cells." (PMID 26036628, 2015). "Here, we specifically examined if HNK could inhibit the stimulatory effect of leptin on EMT and metastatic properties of breast cancer cells." (PMID 26359358, 2015). "Interestingly, leptin treatment decreased the expression of miR-34a in MCF7, SKBR3 and SUM149 breast cancer cells." (PMID 26359358, 2015). "Our results have shown that LDFI inhibits leptin-induced proliferation and motility as well as leptin signalling activation in both ERα-positive and ERα-negative human breast cancer cells." (PMID 25721149, 2015). "The present study aimed to investigate the effects of physiological and supraphysiological levels of leptin (≤1,600 ng/ml) on proliferation in SK-BR-3 and MDA-MB-231 breast cancer cells, two cell lines representative of HER-2-positive and basal-type breast cancer subtypes, respectively." (PMID 24959279, 2014). "A pegylated leptin peptide antagonist (LPA) significantly inhibited breast cancer xenografts hosted by immunodeficient mice without affecting energy balance." (PMID 24587106, 2014). "It has been shown that leptin induces growth and transformation in T47D breast cancer cells unlike normal breast epithelial cells." (PMID 25866478, 2014). "Leptin-induced signalling was analysed in human oestrogen receptor (ER)-positive and negative breast cancer cells using Western blotting, qRT-PCR and radiolabelling assays." (PMID 25482303, 2014). "Epidemiologically, leptin concentrations are higher in patients with breast cancer compared with healthy individuals, independent of body weight." (PMID 24959279, 2014). "In MDA-MB-231 breast cancer cells, which are HER-2-negative, interplay with HER-2/neu cannot account for the observed reduction in proliferation, indicating that growth inhibition at supraphysiological leptin concentrations is HER-2/neu independent." (PMID 24959279, 2014). "First, leptin increases phosphorylation of HER-2/neu, which results in increased proliferation of SK-BR-3 breast cancer cells; second, leptin inhibits ERK1/2 phosphorylation, which is predominant at high leptin concentrations, thereby reducing the effect of increased HER-2/neu signaling." (PMID 24959279, 2014). "Furthermore, leptin transactivated and induced the expression of ER, EGFR, HER2 and IGF-1R in breast cancer." (PMID 24716804, 2014). "Moreover, leptin-induced activation of ERK and STAT3 has been correlated with an increased expression of ERα in breast cancer cells and in breast tumors of nude-mouse xenograft model." (PMID 25505738, 2014). "Moreover, it has been reported that estradiol administration increases leptin mRNA expression in adipose tissue and induces an enhanced leptin and ObR expression in MCF-7 breast cancer cells." (PMID 25505738, 2014). "Interestingly, leptin-induced activation of EGFR was suggested as a potential mechanism that promotes metastasis as well as invasion and, migration of breast cancer." (PMID 24716804, 2014). "Leptin is an upstream regulator of VEGF and VEGFR2 in cancer, including breast cancer." (PMID 24202338, 2013). "In contrast, analysis of leptin expression in women diagnosed with ER-/PR- breast cancer did not demonstrate a correlation between leptin and relapse-free survival outcomes (P = 0.15)." (PMID 24176089, 2013). "More direct evidence from in vitro cell line studies indicated that IGF-1, insulin and estradiol induced the expression of leptin and OBR mRNA in the MCF-7 breast cancer cell line, while in MDA-MB-231 cells, leptin and OBR mRNA expression was induced by insulin or hypoxia." (PMID 23425972, 2013).
breast cancer (continued). "Leptin, collagen VI, and IGF proteins have all been reported to stimulate increases in the transcription and expression of CCND1 (also known as Cyclin D1) in ER expressing breast cancer cells." (PMID 24171117, 2013). "Moreover, we went on to investigate the effects of interactions between leptin and anticancer therapies such as tamoxifen (Tx), 5-fluorouracil (5 FU), taxol and vinblastin, on MCF7 breast cancer cell proliferation." (PMID 23554900, 2013). "Leptin and OB-R are expressed in more than 80% of breast cancer tissue according to immunohistochemistry results in which only cancer cells were evaluated for antigen expression, however, the expression of leptin or OB-R in stroma was not determined." (PMID 24202338, 2013). "Tamoxifen (Tx) treatment reportedly increases serum leptin in patients with postmenopausal breast cancer, regardless of stage of disease." (PMID 23554900, 2013). "Therefore, novel crosstalk between the molecules, Notch, IL-1 and leptin crosstalk outcome, (NILCO), was suggested to play an essential role in the proliferation/migration and expression of pro-angiogenic molecules in breast cancer." (PMID 24202338, 2013). "The other 2 studies displayed higher leptin level in breast cancer patients than that of healthy controls, although no statistical significance was shown." (PMID 23826274, 2013). "In vivo data also show that leptin induced IL-1R tI, VEGF and VEGFR2 as well as growth of breast tumors induced by a carcinogen, 7,12-dimethylbenz[a]anthracene (DMBA) in DIO mice and was reported earlier in human breast cancer xenografts." (PMID 24202338, 2013). "While ASCs isolated from the abdomen of obese subjects demonstrated an increase in leptin expression, the cells failed to elicit an effect on breast cancer cell proliferation or tumor growth." (PMID 24176089, 2013). "This is in contrast other studies in breast cancer survivors who reported correlations between physical activity and several metabolic variables including fasting insulin, HOMA-IR, CRP, leptin, IGF-I and IGFBP-3." (PMID 23855321, 2013). "Aberrant activation of leptin and IGF1 signaling pathways has been shown to result in increased cell proliferation, enhanced epithelial to mesenchymal transition, and greater invasiveness of breast cancer." (PMID 24260287, 2013). "According to a study, the relationship between adiponectin and breast cancer risk is independent of the possible effects of IGF major system components, leptin, BMI, and menopausal status." (PMID 23213569, 2012). "Recent studies have shown that the adiponectin:leptin ratio is reduced in women with breast cancer, and that BMI presents a negative and a positive correlation, respectively, with serum levels of adiponectin and leptin." (PMID 23113882, 2012). "NILCO could represent the integration of developmental, pro-inflammatory and pro-angiogenic signals critical for leptin-induced cell proliferation/migration and regulation of VEGF/VEGFR-2 in breast cancer." (PMID 21731759, 2011). "Furthermore, we previously demonstrated that the disruption of leptin signaling with PEG-LPrA2 markedly reduced the growth of tumors in mouse models of syngeneic and human breast cancer xenografts." (PMID 21731759, 2011). "We also observed similar leptin effects on Notch signaling when we used two human breast cancer cell lines, MCF-7 and MDA-MB-231 (data not shown)." (PMID 21731759, 2011). "To test this hypothesis, we used mouse mammary cancer cell lines (4T1, EMT6 and MMT) that differentially respond to leptin and express OB-R, VEGF/VEGFR-2 and IL-1/IL-1R tI." (PMID 21731759, 2011). "Our recent study indicated that leptin and the leptin receptor (ObR) were significantly overexpressed in primary breast cancer and lymph node metastasis relative to non-cancer mammary epithelium." (PMID 20569445, 2010).
breast cancer (continued). "The relevance of leptin signalling in breast tumorigenesis is reinforced by the observation that both leptin and leptin receptor appear to be significantly overexpressed in breast cancer tissue relative to non-cancer epithelium." (PMID 19223908, 2009). "The analysis of approximately 300 biopsies revealed that leptin is overexpressed in breast cancer, whereas it is absent or expressed at very low levels in normal epithelium or benign tumours." (PMID 19223908, 2009). "In 92% of breast carcinomas examined leptin was found to be overexpressed, but in none of the cases of normal breast epithelium." (PMID 20030801, 2009). "Whereas leptin enhanced the proliferation of various breast carcinoma cell lines, including MDA-MB-468 and MDA-MB-231, it did not have any impact on the migratory activity of these cells." (PMID 20030801, 2009). "To validate in vitro data, we studied whether the leptin/ObR system and HER2 can be coexpressed in breast cancer biopsies and if coexpression of these two systems is associated with specific clinicopathological features." (PMID 18945363, 2008). "Consequently, using breast cancer cell lines naturally expressing HER2 and ObR, we tested if HER2 and ObR can physically interact and if exposure of cells to leptin can transactivate HER2." (PMID 18945363, 2008). "The role of leptin in breast cancer has been substantiated by the fact breast tumors, but not normal mammary epithelium, overexpress both leptin and ObR, and the leptin/ObR system correlates with higher tumor grade and worse prognosis." (PMID 18945363, 2008). "Despite the increasing evidence that leptin impacts human breast cancer cells in vitro, the role of leptin in the development of human breast cancer per se is not clear." (PMID 18162139, 2007). "Some studies have reported that breast cancer subjects have higher serum leptin levels than controls, but others have not." (PMID 18162139, 2007). "The right pane focuses on biochemical assay and genotyping for breast cancer (BC) and control groups, featuring pie charts for genotyping of CD295 and ITLN1, highlighted tests like insulin and leptin, and a comet assay with red fluorescent images." (PMID 41221514, 2025). "Therefore, leptin and AQP1 are promising targets to inhibit VM in breast cancer cells." (PMID 38791252, 2024). "Furthermore, the influence of leptin-induced EMT is not confined to breast cancer; it has also been well documented in various other cancer types, including esophageal adenocarcinoma, cholangiocarcinoma, lung cancer, and prostate cancer." (PMID 38255203, 2024). "In addition, leptin decreases FASN and increases FAO in MCF-7 breast cancer cells, suggesting that leptin-mediated changes in lipid metabolism may support cancer progression." (PMID 39609706, 2024). "However, the impact of leptin on fatty acid metabolism in breast cancer cells has not been investigated when cells are maintained in physiological concentrations of glucose." (PMID 39609706, 2024). "Furthermore, EVs isolated from the adipocytes of obese patients, enriched in leptin and MMP9, could promote the release of MMP9 by breast cancer cells." (PMID 39697630, 2024). "Likewise, in breast cancer, Notch, IL-1 and Leptin Crosstalk Outcome (NILCO) are decisive for leptin upregulatory effects on cell proliferation and migration as well as VEGF/VEGFR-2 expression but the level of NILCO biomarker expression depends on the presence of estrogen receptors." (PMID 37686525, 2023). "Chronic leptin treatment induces EMT in non-tumoral breast epithelial MCF10A cells, which leads to the belief that high leptin expression in normal breast tissue with the assistance of EMT contributes to a higher risk of breast cancer." (PMID 37686525, 2023). "When the Leptin/AMPK signaling pathway was inhibited by acupuncture treatment, it could reduce mitochondrial functional impairment and thus improve post-chemotherapy fatigue in breast cancer patients." (PMID 37542585, 2023).
breast cancer (continued). "A randomised controlled trial conducted among 100 breast cancer survivors, assigned either to exercise or usual care, showed an improvement in BMI and levels of circulating biomarkers, i.e., insulin, IGF-1, adiponectin and leptin, in the exercise group after the exercise intervention." (PMID 36077690, 2022). "The importance of leptin-induced autophagy in ER+ breast cancer cells relies on leptin-induced cancer cell proliferation, as autophagy was shown to participate in the negative regulation of the transcriptional factor E2F1, enabling leptin-mediated cyclin D1 expression." (PMID 36291097, 2022). "According to a recent study, Leptin could induce IL-18 expression in both TAMs controlled by NF-B/NF-B1 and breast cancer cells controlled by PI3K-AKT/ATF-2 signaling, which, eventually, leads to the invasion and metastasis of breast cancer cells." (PMID 36119049, 2022). "Leptin activates the JAK-STAT breast cancer pathway leading to c-MYC and BCL2 expression mediated cell growth and proliferation, whereas estrogen may regulate the development of estrogen dependent breast cancers." (PMID 34225729, 2021). "Despite having different effects on autophagy induction in both breast cancer cell lines, autophagy contributed to leptin-induced migration and ERK phosphorylation and this effect could be due to leptin-induced autophagy in MCF7 cells and to basal autophagic levels in the MDA-MB-231 cell line." (PMID 33763424, 2021). "In addition, leptin-dependent activation of JAK1/2/STAT3/FAK/ERK/GSK3αβ signaling cascade in breast tumor cells enhanced the production of intercellular adhesion molecule 1 (ICAM-1), toward the development of breast cancer bone metastasis." (PMID 33562737, 2021). "Furthermore, studies in human breast cancer patients showed that leptin overexpression has paracrine effects, not always reflected in serum levels, but associated with more aggressive tumors and therapy resistance." (PMID 33644151, 2021). "Taken together, leptin mediated crosstalk between adipocytes and breast cancer cells, which further activated STAT3 not only directly to facilitate PAI-1 expression but also to indirectly affect PAI-1 by repressing miR-34a, thus promoting PAI-1-related EMT to strengthen breast cancer metastasis." (PMID 33371368, 2020). "In nontumor MCF12A mammary epithelial cells and MCF7 breast cancer cells, leptin induces a mesenchymal phenotype, ZEB1 expression, and a “switch” from E-cadherin to N-cadherin, as well as the classic CD24-/CD44+ stem signature, and a larger number of spheres through STAT3." (PMID 33334030, 2020). "Thus, we evaluated the intracellular signaling pathways involved in UPR (e.g., Inositol Requiring 1 (IRE1), PKR-like ER Kinase (PERK), and Activating Transcription Factor 6 (ATF6)) after leptin treatment in breast cancer cells without find any activation." (PMID 31336913, 2019). "The expression of these Rab family components was not modulated by leptin treatment, indicating that leptin effects on exosome release might be dependent on the induction of Tsg101 expression in breast cancer cells." (PMID 31336913, 2019). "In this context, we have shown that leptin, by inducing heat-shock protein 90 (Hsp90) expression, enhances the membrane tyrosine kinase receptor HER2 protein levels and this results in a reduced sensitivity of breast cancer cells to antiestrogen tamoxifen treatment." (PMID 30634494, 2019). "Moreover, it has been demonstrated that leptin from adipose stromal/stem cells induces a differential pattern of gene expression in ERα-positive compared to negative breast cancer cells." (PMID 31380268, 2019). "Therefore, the coexpression of HER2 and the leptin/LEPR system could contribute to increase the activity of HER2, reducing the sensitivity to monoclonal trastuzumab treatments for this type of breast cancer." (PMID 31380268, 2019).